NDRG1 (N-myc downstream regulated 1)
Diseases named in the same sentence as NDRG1 in open-access papers (continued):
Sharing a sentence is not in itself a finding about the gene and the disease.
tumor (continued). "Although the exact functions of Ndrg1 are still unknown, as another effector of HRP, it is also likely to help tumour cells establish themselves." (PMID 15341671, 2004). "In our prior experiments, we found that NDRG1 influences tumor cell metabolic functions by regulating glycolysis and xoxidative metabolism, particularly in A549 cells, where it synergistically interacts with LDHA to promote lactate production and alter the acidic microenvironment of tumor cells." (PMID 40539245, 2025). "Importantly, cells carrying both truncated isoforms of NDRG1 had markedly limited tumor initiation and virtually did not grow at all." (PMID 38983911, 2024). "Notably, Twist, which was consistently inhibited by NDRG1 knockdown in presence of TGFβ1, is not only involved in EMT and metastasis but leads to the generation of cancer stem cells (CSCs), chemoresistance, and tumor progression." (PMID 36594086, 2023). "The results of the tail vein lung metastasis model further revealed that the tumor size and tumor number of HCC lung metastasis were obviously decreased after NDRG1 knockdown, which also signified that the expression of NDRG1 could promote the lung metastasis of HCC cells." (PMID 37208604, 2023). "Overall, this demonstrates the intriguing effect of NDRG1 on the bi-directional cross-talk between PaC and PSC cells, with NDRG1 expression in cancer cells likely reducing their ability to activate neighboring PSCs, which in turn produce fewer tumor-promoting factors to feed PaC progression." (PMID 37345116, 2023). "We found NDRG1 expression was significantly inverse correlated with invasion depth (p = 0.023), whereas DNMT1 was statistically significantly positive correlated with invasion depth (p = 0.049), DNMT3B was significantly positive correlated with the degree of tumor cell differentiation (p = 0.030)." (PMID 34616614, 2021). "There was a higher proportion of negative NDRG1 expression when tumor diameter > 3 cm." (PMID 31831018, 2019). "Moreover, NDRG1 could emulatively antagonize NEDD4-mediated ubiquitylation of p21, increasing p21 expression and inhibit tumor proliferation." (PMID 31831018, 2019). "Cystatin-B (CSTB), leukotriene A-4 hydrolase (LTA4H), protein NDRG1 (NDRG1), and phosphoglycerate kinase 1 (PGK1) from the neoplastic island dataset and collagen alpha-1(VI) chain (COL6A1), integrin alpha-V (ITGAV) and myoglobin (MB) from the tumor stromal dataset were prioritized." (PMID 30185791, 2018). "Moreover, NDRG1 expression negatively correlated to tumor size and clinical TNM stage, suggesting that NDRG1 might act as a tumor suppressor by inhibiting proliferation or inducing apoptosis in CRC." (PMID 29137287, 2017). "However, we did not observe any increased tumor angiogenesis when both BMDMs from Ndrg1 KO mice and cancer cells were implanted." (PMID 26778110, 2016). "NDRG1 also up-regulates the CDK inhibitor, p21WAF1/CIP1, which may mediate its anti-tumor effects." (PMID 26125440, 2015). "Interestingly, in this latter study, although NDRG1 over-expression reduced tumor growth in vivo, cell growth was not affected in vitro, potentially due to in vivo modulatory factors such as those associated with the stroma and angiogenesis." (PMID 26431493, 2015). "However, in the non-tumor tissues, NDRG1 showed a high expression in 196 cases (81.67%) and negative expression in 44 cases (18.33%)." (PMID 23874544, 2013). "Taken together, our data suggest that NDRG1 will not serve as a reliable marker of tumour cells in the pancreas, but may serve as a marker of differentiation." (PMID 16832411, 2006). "Our result show that NDRG1 is upregulated slightly in NBT compared with NB and NS, but NDRG1 levels increase significantly in FtMt-SY5Y cells compared with controls whether by Western blot or immunohistochemistry assay, indicating that elevated FtMt may inhibit tumor cell metastasis via NDRG1." (PMID 25213357, 2015). "It was not clear whether NDRG1 could affect the metastatic ability of tumor cells." (PMID 21912630, 2011).
tumor (continued). "Unlike NDRG1 and NDRG2, NDRG3 facilitates tumor progression and metastasis via activating the WNT/β-catenin pathway." (PMID 40378957, 2025). "Tumor samples consistently exhibited elevated expression levels of SFN, SPP1, and NDRG1 genes, regardless of being paired or unpaired, in comparison to non-tumor samples." (PMID 39066845, 2024). "The expression levels of FCGBP, PABPC1 and NDRG1 were higher and the expression levels of ADH1A, CYP3A4 and ADH1B were lower in tumour tissues than in adjacent nontumour tissues." (PMID 35109839, 2022). "EGb-treated mice had significantly increased mRNA expression of Ndrg1 and p21, two metastasis-related genes, when compared to the PBS control, but only in animals with liver tumors (Tumor), and not in the Normal, non-tumor groups (p < 0.05)." (PMID 29197355, 2017). "There was also a close negative correlation between NDRG1 and nuclear β-catenin and also NDRG1 and CD44 expression in CRC patients with tumor invasion and metastasis to lymph nodes." (PMID 26418878, 2015). "Furthermore, NDRG1 is able to modulate the immune response through several signaling pathways, including the complement pathway, antigen-dependent B cell activation, cytokines and the inflammatory response, and stress induction of HSP regulation, which may be correlated with tumor immunity." (PMID 24260043, 2013). "In contrast, if administration of an Akt inhibitor failed to suppress NDRG1 phosphorylation, this would be a sign that SGK1 activity was elevated, and that the tumours would be likely to be resistant to Akt inhibitors." (PMID 23581296, 2013). "We showed that NDRG1 expression was significantly reduced in CRC tissues compared to the paired non-tumor tissues, further supporting a tumor suppressive function of NDRG1 in CRC as previously reported." (PMID 23874544, 2013). "NDRG1 protein expression showed a negative correlation with the EMT pathway in our T and LM samples (ρ = −0.2, p = 0.098, Spearman correlation analysis), which was consistent with its role as a tumor suppressor." (PMID 41195591, 2026). "Further, in-depth analysis of TCGA-PRAD data revealed significantly higher gene expression profiles for SLC12A2 (P = 0.025), DDAH1 (P < 0.0001), NDRG1 (P = 0.0013), APOE (P < 0.0001), YWHAZ (P = 0.0385), and GDF15 (P < 0.0001), in PCa tumor tissue compared with non-tumoral adjacent tissue." (PMID 33483585, 2021). "Besides, analysis showed that there was a higher proportion of negative expression of NDRG1 when tumor size was > 3 cm (15 and 48 cases of NDRG1 negative expression for size ≤3 cm and size > 3 cm, respectively, p < 0.001), indicating that NDRG1 might be related to tumor proliferation." (PMID 31831018, 2019). "However, unlike NDRG1 and NDRG2, which are widely known as tumor suppressor genes, the role of NDRG3 in cancer is still inconclusive." (PMID 27589737, 2016). "In addition, we found that expression of NDRG1, which was prognostic of RFS but not OS, was mainly increased in TN tumours." (PMID 22067903, 2011). "With the Wilcoxon rank test we find genes such as MYC, CCNE1, KRAS, NDRG1, MLL4 and MTSS1 for which data set specific normal tissue expression may not be significantly different from all tumor samples but is variable between low and high copy number tumor samples." (PMID 22174824, 2011).
cancer (216 papers, 2004 to 2026). A tumor composed of atypical neoplastic, often pleomorphic cells that invade other tissues. "NDRG1 is a multifunctional regulatory human protein implicated in crucial cellular processes and acting as a central hub of a cancer-related interactome." (PMID 41725076, 2026). "Overall, these studies demonstrated NDRG1 was positively correlated with poor clinical outcomes and cancer traits associated with aggressiveness." (PMID 40378957, 2025). "Data from the TCGA Pan‐Cancer Atlas study, covering 22179 patients and 22802 samples across 36 cancer types, showed that NDRG1 frequently undergoes mutations, amplifications, and deep deletions in various cancers, including LUAD." (PMID 40539245, 2025). "NDRG1 suppresses the activation of tPERK/eIF2 and the subsequent autophagy-induced ER stress formation of autophagosomes, increasing cancer cell susceptibility to apoptosis." (PMID 40332138, 2025). "NDRG1 is a stress‐responsive protein activated under hypoxia, a central hallmark of cancer progression." (PMID 40530439, 2024). "NDRG1 functions as a metastasis suppressor with diverse roles, inhibiting the spread of several cancers while also being associated with metastasis in certain tumors, depending on post-translational modifications such as NDRG1 phosphorylation and cleavage." (PMID 37858101, 2023). "The anti-cancer activity of NDRG1 is believed to be associated with its ability to regulate multiple oncogenic signaling pathways and alter cancer cell metabolism." (PMID 37345116, 2023). "Studies also reported that NDRG1 is crucial for controlling cancer cell metastasis and that NDRG1 overexpression is associated with a lower metastasis rate and an increase in 5-year survival in the prostate, breast, cervical, ovarian, and CRC." (PMID 37111248, 2023). "Expression profiles of NDRG1 in clinical samples have revealed association between dysregulation of NDRG1 and poor clinical outcomes, demonstrating the prognostic impact of this protein in the context of cancer." (PMID 37249826, 2023). "Studies in other types of cancers have also revealed dysregulation of protein or mRNA levels of NDRG1 and associations between this abnormal expression pattern and malignant behavior of cancer as reflected in survival time of patients." (PMID 37249826, 2023). "This was associated with a decrease in cancer cell viability that was correlated with an increase in apoptosis when phospho-NDRG1 (Thr346) was reduced by greater than 90%." (PMID 37298315, 2023). "NDRG1 has been strikingly associated with cancer metastasis and thus defined as a metastasis‐suppressor gene in several carcinomas, including CRC." (PMID 36862005, 2023). "For instance, NDRG1 is associated with cancer metastasis via its function in Raf/MEK1/ERK signaling." (PMID 37249826, 2023). "NDRG1 expression has been associated with both chemotherapy- and radiotherapy-resistance in different cancers." (PMID 36497221, 2022). "N-myc downstream-regulated gene 1 (NDRG1), an anti-cancer therapeutic target, has previously been implicated as a CD4+ T cell clonal anergy factor." (PMID 36357486, 2022). "NDRG1 is a stress responsive protein, and its association with hypoxia, a major pathological stress process associated with cancer progression, has been investigated in several studies." (PMID 36497221, 2022). "A high level of NDRG1 was associated with the resistance to ionizing radiation or multiple drug-induced cytotoxicities in various types of cancer cells." (PMID 35563887, 2022).
cancer (continued). "Pertinently for this study, in multiple human cancers increased tissue expression of NDRG1 has been associated with poor outcomes, with in vitro evidence for suppression of NDRG1 as a novel anti-cancer strategy." (PMID 36357486, 2022). "In summary, our current findings represent fundamental advances in the novel mechanism underlying NDRG1's anti-cancer character." (PMID 33994856, 2021). "In the present study, we found that NDRG1 was upregulated in the invasive and radioresistant sublines, over-expressed in the cancer tissues, and associated with poor prognosis in HNC patients." (PMID 34307149, 2021). "The findings discovered a facilitating role of FOXO1/NDRG1 axis which acted as a downstream factor of cancer‐associated fibroblasts." (PMID 34965023, 2021). "Phosphorylation of NDRG1, a regulator of the cytoskeleton that has been implicated in cancer migration and invasion, was dramatically downregulated following the suppression of CIT expression." (PMID 33499898, 2021). "To screen the clues of NDRG1 suppressing cancer, we performed an interaction analysis of NDRG1 with the cancer proliferation‐ and metastasis‐associated genes from the IPA database." (PMID 32537867, 2020). "NDRG1 was also recently reported to be symmetrically upregulated in carcinoma cells and associated with local progression and poor prognosis in the patients with ESCC." (PMID 32106831, 2020). "Loss of NDRG1 functions causes degenerative polyneuropathy and increases malignancy of several human cancers." (PMID 31029158, 2019). "NDRG1 has been shown to be a metastatic suppressor for several human cancers and has been implicated in several physiological processes including cellular differentiation and the G0/G1 arrest." (PMID 25222612, 2014). "It is plausible that NDRG1’s role in cancer progression is regulated by its potential mutations in different cancerous disease, leading to a “loss-of-function” or by the intrinsic genetic mechanism of the specific organs." (PMID 23874544, 2013). "Nevertheless, the association of NDRG1 with cancer progression has been reported with inconsistent observations." (PMID 23874544, 2013). "Additionally, NDRG1 expression was found to negatively correlate with an angiogenesis signature, another hallmark process in cancer." (PMID 40530439, 2024). "Interestingly, a large-scale analysis of mutations in women's cancers (breast, ovarian, endometrial, and cervical) revealed a high mutation frequency (19%) in NDRG1, second only to MYC (22%)." (PMID 38987777, 2024). "NDRG1 is associated with differentiation in other cancers and cell types." (PMID 38893159, 2024). "NDRG1 expression in cancer cells is also associated with inhibition in β-catenin phosphorylation at Ser33/37 and Thr41 residues which protect the cell from β-catenin, a widely known pro-oncogenic transcription factor in the Wnt signaling pathway and thus suppresses cancer metastasis." (PMID 37970212, 2023). "NDRG1 pleiotropy is a known event in several human cancers, although the driving causes are still unknown 3-9." (PMID 36594086, 2023). "Previous studies suggested that NDRG1 could inhibit proliferation and induce apoptosis of cancer cells by regulating Bcl-2 and Ca2+-associated proteins and epithelial–mesenchymal transition (EMT)." (PMID 35795037, 2022). "Thus, NDRG1, 2, and 4 are associated with good prognosis of cancer patients but show mostly downregulated expression in different cancers." (PMID 35563842, 2022). "In addition, MYC and NDRG1 genes located at this locus were also associated with HRD in a pan-cancer manner." (PMID 34976815, 2021). "Our findings indicated that the up‐regulation of NDRG1 by HIF‐1/2α may counteract the cancer‐promoting effect of HIF‐1/2α in VHL‐deficient ccRCC." (PMID 32537867, 2020). "The results of this study imply that autophagy mediated by NDRG1 deficiency via lysosome function impairment may contribute to the sensitivity of cancer cells to chemotherapy drugs." (PMID 28906492, 2017).
cancer (continued). "NDRG1 is associated with carcinoma and liver transplantation, which strongly indicates that it might be closely related to HCC tumourigenesis and therapy." (PMID 28701735, 2017). "Therefore, we assessed CrkII phosphorylation at Tyr221 following alterations in NDRG1 expression, in order to further establish the mechanisms underlying NDRG1-mediated-suppression of cancer cell migration." (PMID 25860930, 2015). "Interestingly, SGK1 and NDRG1 are known to be down-regulated in human cancers as compared with adjacent normal tissues, and increased expression of both of these genes has been associated with better survival of cancer patients (31, –, 35)." (PMID 30337371, 2018). "Although NDRG1 has been extensively studied in relation to cancer and lipid vesicle recycling, its precise molecular mechanisms remain poorly defined." (PMID 41725076, 2026). "Only two studies have previously examined the relationship between NDRG1 and adhesion molecules: one in cultured cancer cells, and one in mice under immersion-induced stress." (PMID 40462946, 2025). "The evidence presented above indicates that NDRG1 serves as a tissue biomarker for cancer management." (PMID 40332138, 2025). "Studies have indicated that the levels of the Ser330 and Thr346 phosphorylated forms of NDRG1 were variably identified in six cancer cell types in vitro, namely, DU-145, PC-3, PANC-1, HT-29, HepG2, and Hep3B." (PMID 40378957, 2025). "Our study lays a solid foundation for future investigations into the role of NDRG1 in cancer biology and therapy." (PMID 40539245, 2025). "Considering this, the current review will discuss the broad range of functions of NDRG1 and its family members, including their roles in disease and potential for cancer treatment." (PMID 40378957, 2025). "Suppressing MiR-1469-5p leads to decreased NF-κB activity, increased NDRG1 levels, and the enhanced expression of E-cadherin, which hinders cancer cell invasion." (PMID 40699746, 2025). "In particular, NDRG1’s role in both apoptotic and anti-apoptotic mechanisms in cancer has been widely explored." (PMID 40378957, 2025). "It facilitates cancer cell growth and invasion by activating the NF-κB pathway, while directly targeting NDRG1, a suppressor of metastasis." (PMID 40699746, 2025). "It was shown that NDRG1 is widely expressed in normal cells while downregulated in many types of cancer." (PMID 39457585, 2024). "One of the genes induced by iron chelators is N-myc downstream regulated gene (NDRG1), which is a well-known metastasis suppressor in various cancer cell types." (PMID 38983911, 2024). "NDRG1 relocates to the trophoblast nucleus under hypoxic stress, and hypoxia is one of the major hallmarks of cancer." (PMID 40530439, 2024). "We thus consider NDRG1 to be a ‘Goldilocks’ cancer protein, where too much or too little has a significant impact on survival." (PMID 40530439, 2024). "Previous studies have demonstrated that phosphorylation at two distinct sites, namely, Ser330 and Thr346, differentially dictates the cellular localization and activity of NDRG1 in various cancer cell types." (PMID 38983911, 2024). "Specifically, depletion of NDRG1 was shown to inhibit proliferation, invasion, migration, and cancer stem cell subpopulations in vitro." (PMID 38611020, 2024). "As previously reported, non-targeted iron chelators, as well as novel thiosemicarbazones, can markedly induce the expression of NDRG1, which subsequently suppresses pro-oncogenic mechanisms within cancer cells." (PMID 38983911, 2024). "Our data, including an HR/NHEJ reporter assay, RAD51 foci, and IHC staining in CDX tissues, demonstrated that NDRG1 enhances HR-mediated DDR in cancer cells." (PMID 38970106, 2024). "Aberrant WNT/β-catenin signaling is well known in PC, with the metastasis suppressor, NDRG1, antagonizing this and other oncogenic signaling pathways in multiple cancer cell-types, including PC cells and tumors." (PMID 38815861, 2024).